ERBB2 (erb-b2 receptor tyrosine kinase 2)
Diseases named in the same sentence as ERBB2 in open-access papers (continued):
Sharing a sentence is not in itself a finding about the gene and the disease.
lung cancer (continued). "The HER family is composed of four members, including EGFR/HER1/ErbB1, HER2/ErbB2, HER3/ErbB3, and HER4/ErbB4, and plays a key role in the pathogenesis of various human solid tumors, including breast, gastric and lung cancers." (PMID 29233126, 2017). "Although PRMT5 and p44 are ubiquitously expressed in all cancer cells, we observed heterogeneous expression of ErbB2, ErbB3, and FGFR3 in lung cancer cells and of some PRMT5/p44-target genes in various cancer cell lines in response to p44 silencing." (PMID 27480244, 2016). "In contrast, lung cancer samples express high levels of PRMT5, WDR77, ErbB2, ErbB3 and FGFR3 and decreased levels of GLIPR1, Leprel1 and BTG2." (PMID 27480244, 2016). "We provided direct evidence that A549 cells constitutively expressed EGFR and ErbB2, while the expression of EGFR increased after BTC stimulation in human lung cancer cells." (PMID 24629040, 2014). "Validation of the model in a panel of 65 lung cancer cell lines perturbed using PI3K and EGFR/ERBB2 signaling pathway inhibitors revealed general rules of the signaling pathway topology downstream of genetically altered EGFR and ERBB2 kinases." (PMID 20111714, 2010). "Here, we present a 10XGenomics scRNA-seq experiment, providing a controlled heterogeneous environment using lung cancer cell lines characterised by the expression of seven different driver genes (EGFR, ALK, MET, ERBB2, KRAS, BRAF, ROS1), leading to partially overlapping functional pathways." (PMID 38307867, 2024). "Human epidermal growth factor receptor 2 (ERBB2, HER2) mutations comprise 3% of lung cancers and are associated with never‐smoker status, female sex, and adenocarcinoma histology." (PMID 38685972, 2024). "Notably, our findings reaffirm the relevance of lung cancer genes, such as CTNNB1, STAT3, HIF1A, HSP90AA1, and ERBB2, integral to various cellular processes and pivotal in cancer genesis and advancement." (PMID 39113883, 2024). "HER-2 or ERBB2 is the human epidermal growth factor receptor 2 which is a membrane-bound receptor tyrosine kinase, acting as a proto-oncogene in some tumors including breast, ovarian, and lung cancer." (PMID 39872522, 2024). "Plenty of studies also pointed out that Afatinib is an irreversible ErbB family blocker, targeting oncogenes such as EGFR, ERBB2 and ERBB3 (that are also included in the oncogene subcomponent of the two cell lines), and is widely used in the treatment of lung cancer." (PMID 37603576, 2023). "In a study of ERBB2-amplified or -mutant lung cancers, co-treatment of lung cancer cells with T-DM1 and the irreversible pan-HER kinase inhibitors neratinib increased uptake of T-DM1, but when the reversible HER2 inhibitor lapatinib was used, a decreased uptake of T-DM1 was seen." (PMID 36831621, 2023). "In particular, EGFR, KRAS, CTNNB1, and ERBB2 genes were captured within the top 20% rank by at least four scRNA-seq workflows, and the two genes EGFR and KRAS, which were most common in lung cancer, were ranked in the top 5.4% and 8.9% by ZW_edgeR_Cov, respectively." (PMID 36944632, 2023). "Importantly, ERBB2 can be deregulated by other mutations, namely missense in other regions, and harbor gene amplification mechanisms, which were not explored in the present study, and could lead to a higher percentage of ERRB2 genomic alterations in Brazilian lung cancer patients." (PMID 36251951, 2022). "The degradation of ErbB2 and EGFR that play direct roles in the progression of breast and lung cancers are degraded by hTid-1 via the proteasomal pathway which is an important indicator as to why hTid-1 can act as a potential molecule of interest in the future to treat cancers." (PMID 35854300, 2022). "Except for the detection of ERBB2 amplification and KRAS mutation in two patients, no other classic lung cancer driver mutations were detected." (PMID 31659278, 2020).
lung cancer (continued). "The difference of recurrence of EGFR/ERBB2/MET is probably due to the different stage of tissues, as the majority data of MSKCC-IMPACT is from late-stage biopsy tissues; while TCGA NSCLC cohort, from early-stage lung cancer primary tumor tissues." (PMID 31739500, 2019). "We hypothesized that these top ERBB2-correlated genes, such as MED24, were crucial players regulating lung cancer development." (PMID 31248101, 2019). "Afatinib, a TKI targeting both EGFR and ErbB2, in combined with anti-EGFR antibody could remarkably attenuate the ErbB2 signaling and in turn resumed the sensitivity of lung cancer and colorectal cancer to TKIs in vitro and in vivo." (PMID 29455669, 2018). "Lung cancer of never smokers exhibited significantly higher ctDNA mutation rates as well as higher EGFR and ERBB2 mutations than ever smokers." (PMID 28472989, 2017). "Meanwhile activations of other signaling pathways, such as ERBB2 and PIK3CA may mediate resistance of lung cancers to EGFR-targeting therapies." (PMID 28591695, 2017). "Why are mutation rates in epidermal growth factor receptor (EGFR) and erb-b2 receptor tyrosine kinase 2 (ERBB2) higher in lung cancer from never smokers than that from smokers?" (PMID 28974261, 2017). "Notably, KRAS, BRAF, ERBB2, PIK3CA, RET, ROS1, ALK, and NRTK1/2/3 have been proposed as prognostic markers, making substantial contributions to genotype-directed therapies for advanced lung cancer." (PMID 36619227, 2023). "Taken together, these data suggest that ERBB2-mutant lung cancer patients may not benefit from immunotherapy." (PMID 35911441, 2022). "Besides EGFR T790M, other resistance mutations can only be detected by the UltraSEEKTM Lung Panel (in BRAF, ERBB2, KRAS and PIK3CA, as well as EGFR C797S) and could be are useful for treatment decision making for lung cancer patients." (PMID 33081150, 2020). "However, overexpression models do not show the physiological role of ERBB2 in the development of lung cancer." (PMID 31248101, 2019). "However, the heterogeneity in ErbB2/3 and FGFR3 expression was observed in lung cancer cells, suggesting regulation of their expression by PRMT5/p44 may be lost in some cancer cells and their functions may be redundant in cancer cell growth." (PMID 27480244, 2016). "Co-activation of MET, AXL, ERBB2, and EPHA2, and co-activation of DDR1 with EGFR, DDR2, HCK, PDGFRA, and FGR is evidence that simultaneous activation of multiple tyrosine kinases may be common in lung cancer." (PMID 23300999, 2013). "ERBB3 bound EGFR, while we could not identify any ERBB2 peptides, suggesting that EGFR may be the primary partner of ERBB3 in these lung cancer cells with activating EGFR mutations." (PMID 24189400, 2013). "Similarly, ErbB2 and ErbB3 were not expressed in the benign lung epithelial cells (left top two panels, indicated by black arrows) but highly expressed in lung hyperplasia (left, circled by red lines) and in most lung cancer cells." (PMID 27480244, 2016). "On the other hand, the prevalence of ErbB family gene fusions in our lung cancer cohort was non-negligible reaching 0.23%, with the majority of these patients carrying EGFR (0.11%) and ERBB2 (0.07%) fusions." (PMID 36369474, 2022). "In summary, our studies demonstrate that PHLDA2 is strongly regulated by EGFR/ErbB2 signaling and inhibits cell proliferation via repressing AKT activation in lung cancers in a negative feedback loop." (PMID 29861842, 2018). "According to a recent report from The Clinical Lung Cancer Genome Project (CLCGP) and Network Genomic Medicine (NGM), a total of two (5 %) LCNEC tumors with ERBB2 amplification, but no SCLC tumors, have been reported, consistent with the present findings." (PMID 25989941, 2015). "ERBB2 and NOTCH1 showed an up-regulation in lung-cancer tissue with increased exposure to both carcinogens, but no staining or a lacking association with exposure in cancer-free samples." (PMID 23028920, 2012).
lung cancer (continued). "Companion diagnoses, such as MSI, ERBB2 staining, EGFR, BRAF, ALK fusion, and BRCA1/2, can be done before the standard treatment, which is another reason why the CGP test is not needed, as the drivers of lung cancer, colon cancer, and melanoma are already known to a certain extent." (PMID 36251535, 2023).
invasive breast carcinoma (834 papers, 1996 to 2026). A carcinoma that infiltrates the breast parenchyma. "The oncogene Erb-B2 receptor tyrosine kinase 2 (ERBB2) is overexpressed in 20–30% of invasive breast cancer and is associated with poor prognosis." (PMID 37875914, 2023). "ERBB4 loss is most frequently found in invasive breast carcinoma and prostate adenocarcinoma, while ERBB2 loss is found in ovarian high-grade serous carcinoma and invasive breast carcinoma." (PMID 36790480, 2023). "ERBB2 is also the most common genetic alterations in invasive breast carcinomas, associated with poor prognosis and response of the tumor to the ERBB2 monoclonal antibody trastuzumab in breast cancer." (PMID 35589822, 2022). "Human epidermal growth factor receptor 2 (HER2 or ErbB2) overexpression is responsible for 20 to 25% of invasive breast cancers, and is associated with poor prognosis." (PMID 34790121, 2021). "Overexpression of ErbB2 (Her2/Neu), is involved in the pathogenesis of nearly 20–30% of invasive breast cancers and is associated with an aggressive phenotype." (PMID 26716506, 2016). "Amplification and/or overexpression of the ERBB2 gene, which encodes human epidermal growth factor receptor 2 (HER2), is seen in 15–20% of invasive breast cancers as determined using fluorescence in situ hybridization (FISH) or immunohistochemical (IHC) staining of the HER2." (PMID 33180796, 2020). "ERBB2 and ERBB3 somatic gain-of-function mutations, which may be targeted by anti-ERBB2 therapies, were reported by high-throughput sequencing studies in 1% and 2% of invasive breast cancers respectively." (PMID 27602491, 2016). "ERBB2 amplification is found in 10–15% of invasive breast carcinomas and classified as HER2-positive by immunohistochemistry." (PMID 38255277, 2024). "This cross-sectional study investigated women with invasive breast cancer who were missing components of receptor status (ER, PR, or ERBB2) by analyzing information about 321 913 cases from the population-based SEER 18 database." (PMID 37615986, 2023). "Approximately 15% to 20% of invasive breast cancers have amplification of ERBB2 gene or overexpression of the HER2 protein." (PMID 37237509, 2023). "To investigate the value for FOXPs to distinguish Breast Invasive Carcinoma samples from normal smples, we performed a ROC curve analysis using ERBB2, BRCA1 and BRCA2 as controls." (PMID 35614183, 2022). "ERBB2 status is a determinant for stratifying invasive breast cancer concerning ERBB2-directed targeted therapy, including ERBB2-targeted monoclonal antibodies and small-molecule tyrosine kinase inhibitors such as lapatinib." (PMID 35431974, 2022). "By analyzing selected tumor types, as invasive breast cancer, colorectal adenocarcinoma and skin cutaneous melanoma, we observed that both ERBB2 and NCR3LG1 transcripts show a variable, heterogeneous and non-correlative expression for each individual patient." (PMID 35036073, 2021). "Overexpression of the epidermal growth factor receptor (EGFR) family member ErbB2 (HER2) drives oncogenesis in up to 25% of invasive breast cancers." (PMID 34439093, 2021). "Approximately 20% of invasive breast cancers have upregulation/gene amplification of the oncogene human epidermal growth factor receptor-2 (HER2/ErbB2)." (PMID 35582612, 2020). "Increased expression of CTSB and CTSL1 leads to increased activity of cathepsins B and L, whose expression correlates positively (p < 0.0001) with high ErbB2 status in primary invasive breast cancer." (PMID 31963147, 2020). "ERBB2 (HER2) is altered in 18% of the breast invasive carcinoma patients queried, 177 of 960 patients, and the logrank test p-value is 0.122." (PMID 33176745, 2020). "While a change in the ERBB2 gene locus is found in 20~30% cases of invasive breast cancers, it is even more prevalent in premalignant breast lesions (~50%), suggesting that a change in ERBB2 gene is an early event in breast carcinogenesis." (PMID 31040372, 2019).
invasive breast carcinoma (continued). "In humans, the ERBB2 gene amplification and overexpression are biomarkers for invasive breast cancer and a therapeutic target." (PMID 31301170, 2019). "Over-expression of the ERBB2 gene or HER2 protein occurs in 15–20% of all invasive breast cancers and has an important bearing on prognosis, as majority of HER2-positive tumors are associated with a more aggressive clinical course and typically a poor outcome." (PMID 30563489, 2018). "Nearly 18% of clinical breast invasive carcinoma samples in TCGA database had shown high amplification of the genomic region that harbored ERBB2, GRB7 and other neighboring genes." (PMID 29414922, 2018). "Our results provide evidence of a new-found, pro-invasive function for Blimp1 in p130Cas/ErbB2 invasive breast cancer and describes its regulation, mechanism of action and in vivo functions." (PMID 28442738, 2017). "ErbB2 is particularly relevant in invasive breast carcinoma as its enrichment results in poor prognosis and shortened survival." (PMID 28306722, 2017). "Specifically, amplification of the HER2 gene (ERBB2) is found in approximately 10% to 20% of invasive breast carcinoma and results in the overexpression of HER2 protein and is associated with a poor prognosis." (PMID 25844540, 2015). "Amplification and overexpression of the proto-oncogene HER2 (ERBB2) are found in approximately 15 to 20% of all invasive breast cancers." (PMID 25994018, 2015). "HRGβ is endogenously overexpressed in 30% of invasive breast cancers, and its overexpression correlates with increased levels of pERBB2 in 67% of the cancers even though ERBB2 is expressed at low levels." (PMID 25386657, 2014). "Aberrant ErbB2 activation is found in about 25%–30% of invasive ductal breast carcinomas, however, up to 85% of mammary ductal carcinomas in situ (DCIS), which are early non-invasive mammary carcinomas, also overexpress ErbB2." (PMID 24709902, 2014). "In this study we assessed the clinical significance of ErbB-2 nuclear localization in primary invasive breast cancer." (PMID 22356700, 2012). "Overexpression of human epidermal growth factor receptor type 2 (HER2, also referred to as HER2/neu or ErbB-2), a 185-kD receptor first described more than two decades ago, occurs in 20 to 30% of invasive breast cancers." (PMID 19208263, 2009). "In our study, 175 cases diagnosed as invasive breast cancer were examined to determine the frequency of chromosome 17 polysomy in different ERBB2 IHC subgroups." (PMID 15743507, 2005). "Approximately 25% of invasive breast cancers exhibit ErbB2 gene amplification and the rate of ErbB2 gene amplification or protein overexpression in ductal carcinoma in situ (DCIS) is the same or higher than in invasive cancers." (PMID 16371159, 2005). "In patients with invasive breast cancer, ErbB2 is positively correlated with the HSF1/LDHA axis." (PMID 40593465, 2025). "Additionally, the performance of ERBB2 on breast invasive carcinoma and bladder urothelial carcinoma was found to be most prominent among all target-indication combinations, although it was moderately expressed in many normal tissues." (PMID 40005994, 2025). "Between 15 and 20% of primary invasive breast carcinomas show overexpression and/or amplification of the Human Epithelial Growth Factor Receptor-2 (HER2), a transmembrane glycoprotein with tyrosine-kinase activity encoded by the ERBB2 gene on chromosome 17 (17q12)." (PMID 38893129, 2024). "A retrospective study conducted in 96 specimens from patients with invasive breast cancer with amplification of the ERBB2 gene in the entire tissue section demonstrated there was intratumoral heterogeneity in the ERBB2 gene amplification in a subset of patients." (PMID 36291900, 2022). "Notably, chr8 harbors the MYC gene, which is one of the most frequently amplified genes in human cancers, whereas chr17 contains the ERBB2 gene, which is amplified in about 20% of all invasive breast cancers." (PMID 34395272, 2021).
invasive breast carcinoma (continued). "ERBB2 mutations are more common in invasive lobular carcinoma (ILC) than in invasive breast carcinoma of no special type (IBC-NST)." (PMID 34257600, 2021). "ERBB2-mutated BCs comprised invasive breast carcinoma of no special type (21/35, 60%), classic invasive lobular carcinoma (12/35, 34.3%), and pleomorphic invasive lobular carcinoma (2/35, 5.7%)." (PMID 34257600, 2021). "Moreover, the elevated protein expression of Grb7 is strongly correlated with ERBB2 gene amplification as well as ERBB2 overexpression in invasive breast cancer." (PMID 31083325, 2019). "Interestingly, GRB7 and ERBB2 are co-amplified in 15% of invasive breast cancers and 17–19% of gastric adenocarcinomas." (PMID 24874471, 2014). "Library 1 (Lib_1) was prepared from the human breast cell line C5.2, which over-expresses the oncogene ERBB2, and library 2 (Lib_2) was prepared from a pool of 5 invasive breast carcinoma samples that stained positively for ERBB2 according to immunohistochemistry analysis." (PMID 21210970, 2010). "Furthermore it had been shown that proteolytic activation of PAR1 by thrombin induces persistent transactivation of EGFR and ErbB2/HER2 in invasive breast carcinoma." (PMID 19538737, 2009). "However, amplification of the HER2/neu (ErbB2) gene, and overexpression of the receptor occurs in only a fraction (up to 25%) of invasive breast cancers." (PMID 17923870, 2007). "Moreover, invasive breast cancer includes at least four major molecular subtypes, which differ by their expression of estrogen receptor alpha (ER), progesterone receptor (PR), receptor tyrosine-protein kinase erbB-2 (Her2), and the proliferative status of the tumor." (PMID 27562113, 2016). "Together, these data provide valuable insights into the differential expression patterns of ITGB6, ERBB2, RAB5A, RAB7A, and GDI2 in breast invasive carcinoma." (PMID 39630893, 2024). "To further investigate molecular differences by race, we analyzed established IBC biomarkers by SRR, including gene expression of ESR1 (ER) and ERBB2 (HER2), as well as the intrinsic subtypes defined by PAM50 in invasive breast cancers." (PMID 39223670, 2024). "In this cohort study of 687 Black women with invasive breast cancer, West African genetic ancestry was associated with shorter disease-free survival, particularly among the hormone receptor (HR)–positive/human epidermal growth factor receptor 2 (ERBB2 [formerly HER2])–negative subgroup." (PMID 39652347, 2024). "Of note, a cohort of 26 invasive breast cancer patients, which represents about 18.8% and 3.4% of the total SIRT6 and ERBB2 gene amplifications, respectively, harbors a concomitant gene amplification of both SIRT6 and ERBB2." (PMID 38081972, 2023). "Previous reports suggest that proteolytic activation of PAR1 by thrombin-dependent MMP activity resulted in the persistent activation of EGFR and ErbB2/HER2 through extracellular signal-regulated kinase-1 and kinase-2 (ERK1/2) in invasive breast carcinoma." (PMID 30065181, 2018). "ERBB2 (HER2) is a well-characterized membrane receptor in the EGFR family and a therapeutic target in invasive breast carcinoma." (PMID 24091566, 2013). "Prognostic and predictive markers utilized in invasive breast carcinoma are limited and include ER, PR, Ki67, and ERBB2 (HER2)." (PMID 24091566, 2013). "Human epidermal growth factor receptor 2 (HER2), also known as receptor tyrosine-protein kinase ERBB2, belongs to the epidermal growth factor receptor (EGFR) family, and it is one of the most important oncogenes in invasive breast cancer." (PMID 22905152, 2012). "Among 1990 patients with node-positive, hormone receptor-negative, or ERBB2-positive invasive breast cancer, 295 of 370 women (79.7%) with diabetes and 1464 of 1620 women (90.4%) without diabetes received chemotherapy." (PMID 38717774, 2024).